CDR1 (cerebellar degeneration related 1)
Synonyms: CDR62A; CDR34; formerly CDR
Gene: Long non-coding RNA gene on chromosome X (140,783,578 to 140,784,366, reverse strand). Ensembl gene ENSG00000288642.
Diseases named in the same sentence as CDR1 in open-access papers:
CDR1 is named in the same sentence as 28 diseases in open-access papers, as found by Europe PMC text mining. Sharing a sentence is not in itself a finding about the gene and the disease. The quoted sentences say what the papers report.
bladder cancer (3 papers, 2018 to 2020). "In a study in 201813, a circular RNA (Cdr1) was used for therapeutic purposes, by targeting miR-135a, up-regulating p21 and thus decreasing proliferation of bladder cancer cells." (PMID 33139749, 2020). "Overexpression of Cdr1 reduced cellular proliferation, migration, and invasion in the human bladder cancer cell lines EJ and T24 in vitro, and retarded tumor growth in Balb/c nude mice in vivo." (PMID 31080413, 2019). "For example, the circular form of of CDR1 is able to sponge miR-135a in bladder cancer and exerts anti-carcinogenic functions." (PMID 29973643, 2018). "Similarly, in another bladder cancer study the circRNA Cdr1 (also known as ciRS-7) is downregulated in cancer cells as compared to normal adjacent tissue." (PMID 31080413, 2019).
Candidemia (3 papers, 2006 to 2019). A form of invasive candidiasis where species of CANDIDA are present in the blood. "Among the 13 diagnostic antigens for acute candidemia, three are associated with drug resistance (Cdr1, Cdr4, and Yor1)." (PMID 20361054, 2010). "Our finding that the expression of CDR1 is repressed by serum raises the question as to how does CDR1 contribute to the drug resistance in C. albicans causing candidemia." (PMID 16839415, 2006).
cerebellar degeneration (3 papers, 2015 to 2021). Degeneration of the cerebellum. "Cerebellar degeneration related protein 1 (CDR1) is expressed in the cerebellum, and CDR1 antibodies have been associated with paraneoplastic cerebellar degeneration (PCD)." (PMID 29844866, 2018). "For example, at the time of writing, no Gene Ontology annotations have yet been ascribed to the human CDR1 gene, known to contribute to paraneoplastic cerebellar degeneration (OMIM:302650)." (PMID 25861967, 2015). "Furthermore, CDR1 is a putative neuronal protein identified in individuals with cerebellar degeneration." (PMID 33922640, 2021).
diabetes (3 papers, 2017 to 2022). "Till date, CDR1, cerebellum degeneration-related antigen 1, also termed as ciRS-7, is most known diabetes-related circRNA, and it is produced from a natural antisense strand of CDR1." (PMID 35184688, 2022). "Additionally, various circRNAs are indicated for overexpression in non-cancer diseases, such as circRNA Cdr1 in myocardial infarction and Cdr1 as in diabetes." (PMID 32199127, 2020). "CDR1 gene transcripts (also known as circular RNA sponge for miR-7, CiRS-7) abundantly express in brain, neuroblastoma lines, renal cell carcinoma lines etc., and influence many diseases including diabetes, prion disorders and cancers." (PMID 28410211, 2017).
breast cancer (2 papers, 2018 to 2022). A primary or metastatic malignant neoplasm involving the breast. "Endogenous expression of CDR1 in the ovarian cancer cell line OVCAR-3 and the breast cancer cell line BT474 showed that CDR1 was localized to the cytoplasm and plasma membrane." (PMID 29844866, 2018). "This indicates that CDR1 antibodies can be associated with PCD in both ovarian and breast cancer." (PMID 29844866, 2018). "CDR1 was also present in ovarian and breast tumors, as well as in ovarian and breast cancer cell lines, but was not present in normal breast or ovarian tissue." (PMID 29844866, 2018).
candidiasis (2 papers, 2022 to 2025). Infection with the organism Candida. "The ATP-binding cassette (ABC) transporter Cdr1 is a key mediator of antifungal drug resistance in Candida albicans, a major pathogen responsible for invasive candidiasis." (PMID 41450950, 2025). "The low MECs (25 μg/mL) that caused a reduction in the MICFCZ values of at least fourfold with the clinical isolates of Candida, highlighted A. communis and S. atriplicifolium as promising sources of Mdr1 and Cdr1 inhibitors to augment FCZ activity in the treatment for azole resistant candidiasis." (PMID 36224581, 2022).
glaucoma (2 papers, 2021 to 2023). Increased pressure in the eyeball due to obstruction of the outflow of aqueous humor. "Furthermore, the synthetic CDR1 peptide ASGYTFTNYGLSWVR induced neuroprotective effects on retinal ganglion cells (RGCs) in an organ culture model for glaucoma, and was also accompanied by specific proteomic changes in the CDR1-treated retinal explants." (PMID 34440217, 2021). "In addition, we also identified the cytoskeleton-regulating protein moesin (MSN) with high abundance in CDR1-treated retinae compared to CTRL, whose phosphorylation state was also associated with dysfunction of the blood-retina barrier in an experimental glaucoma model." (PMID 37509196, 2023). "Hence, the increased expression of PDHA1 (subunit of PDH) seems to have a great significance on the CDR1-induced RGC neuroprotection ex vivo and also highlights the relation between the pathogenesis of glaucoma and phosphoprotein cell signaling." (PMID 37509196, 2023).
glioma (2 papers, 2016 to 2022). A benign or malignant brain and spinal cord tumor that arises from glial cells (astrocytes, oligodendrocytes, ependymal cells). "In addition, among the negatively correlated genes, CDR1 decreases the proliferation, migration and invasion of glioma cells and promotes cell apoptosis." (PMID 34953037, 2022).
neuroblastoma (2 papers, 2017 to 2018). Neuroblastoma (NB) is the most common solid, extracranial childhood tumor. "CDR1 mRNA is also highly expressed in neuroblastoma and renal cell carcinoma, but has not been found in breast and ovarian cancer cell lines." (PMID 29844866, 2018).
ovarian tumors (2 papers, 2018). "In summary, we found that CDR1 is expressed in cerebellar tissue, as well as in breast and ovarian tumors and cancer cell lines, but not in normal ovarian or breast tissue." (PMID 29844866, 2018).
breast tumors (1 paper, 2018). "In this study, we examined CDR1 expression in cerebellum and in ovarian and breast tumors, as well as the intracellular localization of CDR1 in cancer cells in culture." (PMID 29844866, 2018). "Since we found the 37-kDa band in untransfected HeLa lysates, in ovarian and breast tumor lysates and in lysates from all ovarian cancer patients examined, it is likely that this is the CDR1 isoform that is naturally expressed in the body." (PMID 29844866, 2018). "CDR1 protein has previously been found in Purkinje cell extract and in breast tumor lysate from a patient with PCD, but not in breast tumor lysate from a patient without PCD." (PMID 29844866, 2018).
diabetic nephropathy (1 paper, 2022). "Although previous studies on diabetic nephropathy had the limitation of being restricted to animal experiments, the findings suggest that the circRNA_0001946–miR671-5p–CDR1 axis is a potential therapeutic target for diabetic nephropathy." (PMID 36551885, 2022).
fungal infection (1 paper, 2022). "Therefore, the inactivation of Cdr1 will enhance the antifungal activity of azoles against fungal infection." (PMID 36618949, 2022).
lung carcinoma (1 paper, 2015). "Among the classifier genes that are up-regulated in lung cancer, NOVA1 and CDR1 are predominantly expressed in neurons, but are also expressed in tumors and are associated with para-neoplastic antibodies in several malignancies, including small-cell lung cancer." (PMID 25944280, 2015).
ovarian carcinoma (1 paper, 2018). A malignant neoplasm originating from the surface ovarian epithelium. "In this study, we have therefore characterized CDR1 by examining the expression of CDR1 protein in cerebellum, ovarian cancer and cancer cell lines." (PMID 29844866, 2018).
infection (6 papers, 2013 to 2021). The state of being infected such as from the introduction of a foreign agent such as serum, vaccine, antigenic substance or organism. "Overexpression of CDR1 caused dwarfing and resistance to the virulent pathogen Pseudomonas syringae and CDR1 deficiency resulted in increased susceptibility to infection by this pathogen." (PMID 23696830, 2013). "Our findings suggest that pharmacologically targeting Cdr1 in combination with azoles may be an effective strategy to control infection caused by azole-resistant isolates of C. auris." (PMID 33353950, 2020). "In nearly all of the isolates, ALS1, HWP1, SAP4–SAP6, LIP1–LIP10, PLB1, and PLB2 were expressed after infection of the cell line A431, whereas CDR1 was expressed in 20 (51.3%) and ALS3 in 14 (35.8%)." (PMID 28058052, 2016). "Collectively, our findings demonstrate pharmacological inhibition of Cdr1 function may be an effective way to control infection with azole-resistant isolates of C. auris." (PMID 33353950, 2020). "In this work, to analyse the expression patterns of ALS1–ALS3, HWP1, SAP1, SAP4–SAP6, LIP1–LIP10, PLB1-PLB2, CDR1, and MDR1, we implemented an in vitro model of infection of human vaginal cells with C. albicans strains isolated from women with VVC." (PMID 28058052, 2016).
tumor (6 papers, 2017 to 2024). "Specifically, the most well-known circular RNA ciRS-7, which is spliced from the antisense transcript of the CDR1 gene, harbors extensive miR-7 binding sites to mediate miR-7 expression in tumor cells." (PMID 29207676, 2017).
cancer (5 papers, 2017 to 2021). A tumor composed of atypical neoplastic, often pleomorphic cells that invade other tissues. "We found that CDR1 was localized to soma and dendrites of Purkinje cells, whereas in cancer cells CDR1 was localized to protrusions of the plasma membrane." (PMID 29844866, 2018). "We found that CDR1 was expressed in a polarized pattern towards one of the edges in the cancer cells in culture." (PMID 29844866, 2018). "This polarized expression could be seen in single HeLa cells overexpressing CDR1, and in colonies of cancer cells that express CDR1 endogenously." (PMID 29844866, 2018). "The 37-kDa isoform of CDR1 was abundant in the cerebellum and Purkinje cell lysates, as well as in breast (BT474) and ovarian (OVCAR3) cancer cell lysates." (PMID 29844866, 2018). "In addition, the protein CDR1, an APCCDH1 substrate, binds c-MYC to activate its transactivation; elevated accumulation of CDR1 in cancer cells as a result of APC inhibition or defect promotes c-MYC oncogenic function." (PMID 32805721, 2020). "However, why CDR1 antibodies are so rarely found in cancer patients is not known." (PMID 29844866, 2018).
CDR1 also shares sentences with these, for which no sentence is quoted: Alzheimer disease (1 paper); diabetic cardiomyopathy (1); infarct (1); melanoma (1); myocardial infarction (1); prostate carcinoma (1); renal carcinoma (1); renal cell carcinoma (1); small cell lung carcinoma (1); vulvovaginitis (1).